CASP1 (caspase 1)
Diseases named in the same sentence as CASP1 in open-access papers (continued):
Sharing a sentence is not in itself a finding about the gene and the disease.
endometrial cancer (continued). "Another study assessed the expression of four pyroptosis-related molecules (NLRP3, cleaved caspase-1 p20, cleaved gasdermin D, and CHMP4B) in 351 endometrial cancer patients via immunohistochemistry and analyzed their associations with clinical, pathological, and survival outcomes." (PMID 40718836, 2025). "Upregulated expression of NLRP3, caspase-1, and GSDMD were detected in endometrial cancer tissues (N = 546) compared with normal endometrium (N = 35) in TCGA database, significantly difference was seen in NLRP3 and GSDMD in sample type and histological types (P < 0.05)." (PMID 31924176, 2020). "Negative or weak expression of caspase-1 was observed in 20% (3/15) of endometrial carcinoma cases, and 80% (12/15) showed moderate -to-strong expression, while all benign endometrial specimens showed negative or weak expression of caspase-1 (n = 6)." (PMID 31924176, 2020). "Additionally, immunohistochemistry (IHC) and protein immunoblotting studies have shown overexpression of NLRP3, caspase-1, and GSDMD in human endometrial cancer tissues and cell lines, with moderate to strong positive staining for these proteins in tumor sections." (PMID 40718836, 2025). "Studies have reported that pyroptosis-related protein caspase-1, NLRP3 and GSDMD were highly expressed in endometrial cancer tissue, and hydrogen could inhibit the growth of endometrial cancer by inducing GSDMD-mediated pyroptosis through a ROS/NLRP3/caspase-1 pathway." (PMID 34381721, 2021). "Furthermore, our investigation revealed that high expression of NLRP3, the initiator of the canonical pyroptotic pathway responsible for activating caspase-1, was linked to adverse RFS, specifically in advanced endometrial cancer, although not across all stages of endometrial cancer." (PMID 38562170, 2024). "Therefore, we hypothesize that GSDMD is the terminal protein in the pyroptotic sequence in endometrial cancer cells, and that GSDMD-mediated IL-1β secretion occurs via the ROS-NLRP3-caspase-1 signaling pathway is induced by activating effector molecular hydrogen." (PMID 31924176, 2020). "There was a trend in increased expression of pro-caspase-1 in hydrogen treated endometrial cancer cell lines, however significant difference was not seen (P > 0.05), we thought it might be related to the effect time of hydrogen on endometrial cancer cell lines which need to be further investigated." (PMID 31924176, 2020).
liver disease (11 papers, 2015 to 2025). "However, the role of inflammasomes in HBV-related liver disease remains largely obscure, and studies of caspase-1 in ACLF caused by acute exacerbation of CHB are scarce." (PMID 31429707, 2019). "Based on the results of the present study, it can be concluded that NLRP3 plays an important role in liver disease progression during HCV infection through CASP1 activation." (PMID 36376416, 2022). "Immunohistochemical analysis showed that positive immunostaining of NLRP3 and its activation marker CASP1 was detectable as brown granules in the cytoplasm of hepatocytes in liver sections of all patients with HCV-related liver disease." (PMID 36376416, 2022). "NOD-like receptor pyrin domain containing 3 (NLRP3) is a microbial and danger signal sensor that acts as a regulator of inflammation via activation of Caspase-1 (CASP1) and has been identified as a major contributor to human liver diseases." (PMID 36376416, 2022). "Caspase-1 plays an important role in the pathogenesis of various liver diseases in vivo or in vitro, not only as an inflammatory mediator but also as a hepatocyte apoptosis mediator." (PMID 31429707, 2019). "We evaluated the expression levels of caspase-1 in HBV-related liver disease and assessed its utility as a biomarker predicting the severity of ACLF." (PMID 31429707, 2019). "Specifically, blocking key molecules such as NLRP3 and Caspase-1 could help attenuate the pathological processes associated with conditions such as NASH and other liver disorders." (PMID 40398602, 2025). "In conclusion, NLRP3 plays an important role in liver disease progression during HCV infection via CASP1 activation and might be a promising therapeutic target." (PMID 36376416, 2022). "Previous liver disease studies support our observations for Casp-1–/– and IL-1R–/– mice." (PMID 32431709, 2020). "In addition to the classical NLRP3 inflammasome–caspase-1 cytokine activation pathway, serine proteases from immune cells are also potent cytokine activators contributing to liver disease progression." (PMID 31507607, 2019). "First, we measured hepatic the mRNA and protein levels of caspase-1 in HBV-related liver disease." (PMID 31429707, 2019). "It has proposed that mature IL-1β secretion requires appropriate process by NLRP3 activation and caspase-1 cleavage in various liver diseases, including alcoholic steatohepatitis, viral fulminant hepatitis, non-alcoholic fatty liver disease, and heat stroke-induced liver injury." (PMID 29692782, 2018). "NOD-like receptor protein 3 (NLRP3) inflammasome, a multiprotein complex, contributes to the development of liver disorders, such as alcoholic steatohepatitis, viral fulminant hepatitis, and non-alcoholic fatty liver disease, through processing caspase-1 cleavage and IL-1β secretion." (PMID 29692782, 2018). "The present study demonstrated increased serum NLRP3 levels in patients with HCV-related liver disease in parallel with up-regulation of NLRP3 and its activation marker CASP1 in the liver." (PMID 36376416, 2022). "The effect of liver disease on gene expression was confirmed in multivariable models after adjustment for potential confounders (age, sex, BMI): all the inflammasome components (P2X7R, P2X4R, NLRP3, CASP1, AIM2, IL-2) were significantly related to the liver disease (0.0007 < p <0.037)." (PMID 35806450, 2022).
Myocardial fibrosis (11 papers, 2018 to 2025). "Enhanced activation of NLRP3-inflammasome in AMs increases caspase-1 cleavage and caspase-1-mediated apoptosis, releases inflammatory cytokines, recruits macrophages and other immune cells, and induces myocardial fibrosis and promotes the formation of AF maintenance substrates." (PMID 38077349, 2023). "Inhibition of ASC and caspase-1 could decrease inflammatory responses and myocardial fibrosis." (PMID 35310035, 2022). "Moreover, recent research has shown that GSDMD-mediated pyroptosis plays a significant role in the occurrence and development of DN, and AS-IV could alleviate MI-induced myocardial fibrosis and cardiac remodeling by suppressing the ROS/Caspase-1/GSDMD signaling pathway." (PMID 38572426, 2024). "The ceRNA regulatory network, Kcnq1ot1/miR-214-3p/caspase-1/TGF-β1, plays an important role in the regulation of myocardial fibrosis in DCM." (PMID 30250027, 2018). "Glibenclamide reverses ROS production and caspase-1 activity induced by a high-fat diet, downregulates the TGF-β1-pSmad2/3-NLRP3 signaling pathway, inhibits profibrotic factors such as MMP-9, and alleviates myocardial fibrosis." (PMID 40869128, 2025). "In vivo experimental results showed that LGZGD could significantly improve cardiac function, alleviate myocardial fibrosis, reduce the level of inflammatory factors, and inhibit the activation of NLRP3/Caspase-1/GSDMD signaling pathway." (PMID 35615687, 2022). "Moreover, LQF group inhibited the protein expressions of NLRP3, ASC, and cleaved caspase-1; these data supported the notion that LQF alleviates myocardial fibrosis by inhibiting the activation of NLRP3 inflammasome." (PMID 35310035, 2022).
neuroblastoma (11 papers, 2012 to 2024). Neuroblastoma (NB) is the most common solid, extracranial childhood tumor. "Alvarez and Munoz-Fernandez studied caspase-1 activity in the human neuroblastoma cell lines, SK-N-MC cells, and showed a two-fold increase in caspase-1 activation after treating these cells with 20 ng/mL of TNF-α when compared to untreated cells." (PMID 27187378, 2016). "We show here that exposure of a human neuroblastoma cell line (SK-N-MC cells) to TNF-α promotes ROS-mediated caspase-1 activation and IL-1β secretion." (PMID 23940760, 2013). "It is interesting to note that due to the model used in this study, as neuroblastoma cells, in the complex interplay between malignant cells and their microenvironment, caspase-1 activation complexes have contrasting roles." (PMID 23940760, 2013). "Since we previously detected that AAP induced an increase in caspase 1 activity in neuroblastoma cells and that the IL-1β gene contains the NFkB response element in its promoter region, we decided to analyze IL-1β levels in AAP-treated SH-SY5Y cells." (PMID 23166834, 2012). "In addition, in a model of amyotrophic lateral sclerosis (ALS), characterized by an increase in the production of ROS, specific inhibition of caspase 1 prevented activation of caspase 3 in neuroblastoma cells." (PMID 23166834, 2012). "In addition, we found that AAP increased caspase-1 activity, the unique caspase that processes pro-IL-1β into mature IL-1β, in neuroblastoma cells." (PMID 23166834, 2012). "Thus, the authors concluded that BPA could induce pyroptosis in neuroblastoma cells through the NLRP3/caspase-1/GSDMD pathway, mediated by ER." (PMID 37855918, 2024). "However, considering that mutant SOD1 promotes apoptosis in oxidatively stressed neuroblastoma N2a cells by activating caspase-1 and increasing mature IL-1β secretion, we postulate that AAP-induced ROS production may be responsible for caspase-1 activation." (PMID 23166834, 2012). "When co-cultured with the SH-SY5Y neuroblastoma cells under hypoxic conditions, the levels of NLRP3 and cleaved caspase-1 in BV-2 cells were significantly increased, but decreased after TAK-202 treatment." (PMID 33530496, 2021). "In contrast to epithelial tumors (A549, MCF7 and PC3), Caspase 1 inhibition triggered the release of CCL11 and CCL26 in a neuroblastoma cell line." (PMID 33613529, 2020). "The human neuroblastoma cell line SH‐SY5Y used in this study did not express CASP1 and GSDMD, thus excluding canonical inflammatory pyroptosis." (PMID 37646198, 2023). "Interestingly, no caspase 1 activation was detected neither in SK-N-MC or U87MG cells suggesting that this event was specific for SH-SY5Y neuroblastoma cell line." (PMID 23166834, 2012).
periodontal disease (11 papers, 2013 to 2025). "This is particularly relevant in the context of periodontal disease, where Caspase-1-mediated pyroptosis has been implicated in tissue destruction and bone resorption." (PMID 40896724, 2025). "Considering the attenuation of bone resorption in Casp1-KO mice, the increase in the number of osteoclasts associated with the induction of experimental periodontal disease was surprisingly similar in all genotypes." (PMID 32385413, 2020). "As an inceptive study, these results suggest that Nlrp3 inflammasome does not play a significant role in inflammation and bone resorption in vivo and that Caspase-1 has a pro-resorptive role in experimental periodontal disease." (PMID 32385413, 2020). "In RAW macrophages, PBMCs and transgenic mice, the IL37 variant increases expression of IL-1β and IL-6, inducing more severe periodontal disease, while IL-37 protein production is impaired and shows reduced cleavage by caspase-1." (PMID 30206230, 2018). "Thus, understanding the triggers for P2X7−dependent ROS generation and caspase-1 activation could aid in drug discovery and development of therapeutic approaches for diseases associated with P. gingivalis, such as periodontal disease and cardiovascular disease." (PMID 23936165, 2013). "Nevertheless, the precise role of caspase-1 in the pathogenesis of periodontal disease remains unknown." (PMID 36794778, 2023). "Moreover, Caspase-1 was expressed in clinical samples collected from patients affected by periodontal disease." (PMID 34069836, 2021). "Caspase-1 is considered another inflammasome component with a specific role in periodontal disease." (PMID 34069836, 2021). "Considering that bacterial LPS is a major disease-inducing antigen in periodontal diseases, we assessed the role of Nlrp3 and Caspase-1 on the expression of the inflammation- and macrophage phenotype-associated genes Il-10, Il-12 and Tnf-α in primary bone marrow-derived macrophages." (PMID 32385413, 2020). "This inceptive study intends to contribute to bridge this gap of knowledge, by providing insights into the role NLRP3 inflammasome and of Caspase-1 on inflammation and alveolar bone resorption in a murine model of bacterial-induced experimental periodontal disease." (PMID 32385413, 2020). "In summary, NLRP3 inflammasome did not play a significant role in inflammation and bone resorption in the heat-killed Aa-induced periodontal disease model; whereas lack of Caspase-1 attenuated inflammatory bone resorption and the infiltration of PMNs." (PMID 32385413, 2020). "In addition, these results indicate that other inflammatory pathways are involved in the pathogenesis of periodontal diseases, as inflammation and alveolar bone resorption were not completely abrogated in either Nlrp3- or Casp1-KO mice." (PMID 32385413, 2020).
ZIKV infection (11 papers, 2017 to 2025). "Activation of caspase-1 in response to ZIKV infection was demonstrated using the fluorescent reporter of caspase-1 substrate FAM-FLICA, together with the antibodies recognizing the ZIKV envelop proteins (Env) and thus marking infected cells." (PMID 33208442, 2021). "Taken together, we demonstrate that ZIKV infection induces severe inflammatory responses in mice through Casp-1-mediated activation of IL-1β." (PMID 29317641, 2018). "In C57BL/6 WT mice, ZIKV infection activates IL-1β production and induces inflammatory responses, and Casp-1 is involved in such activations." (PMID 29317641, 2018). "Furthermore, ZIKV infection reduced the levels of CASP1-p20 in both iBMDMs and BMDMs treated with LPS plus Ni, as well as the levels of CASP3-p17 and CASP7-p20 in both cell types treated with TNF plus CHX." (PMID 39976465, 2025). "Given the key role of NLRP3 inflammasome in innate immune responses by activating caspase-1 to promote IL-1β secretion and pyroptosis, we examined whether ZIKV infection stimulates IL-1β secretion through NLRP3 inflammasome activation in THP-1 cells." (PMID 37191498, 2023). "In fact, expression of pro-caspase-1 was upregulated in both cell lines after ZIKV infection." (PMID 35446851, 2022). "Nevertheless, in our preliminary assessment for the therapeutic effect of caspase-1 inhibitor VX765, its inhibition of cell death and inflammation caused by ZIKV infection was suboptimal, suggesting that ZIKV may also induce other forms of inflammation-associated cell death." (PMID 41263557, 2025). "Moreover, in A129 mice, ZIKV infection significantly induces IL-1β production in the brain, spleen, liver and kidney, but such inductions are significantly suppressed by the caspase-1 inhibitor (Ac-YVAD-cmk), confirming that Casp-1 is required for ZIKV-induced activation IL-1β." (PMID 29317641, 2018). "Interestingly, ZIKV infection induced the levels of both pro-caspase 1 and the cleaved caspase-1." (PMID 29167459, 2017). "We further elucidated that ZIKV infection drives PANoptosome formation, with RIG-I nucleating the complex by recruiting ASC, caspase-1, NLRP3, caspase-8, and RIPK1 to activate PANoptosis." (PMID 41263557, 2025). "In this study, we uncover that RIG-I, a cytoplasmic dsRNA sensor, can recruit caspase-8, RIPK1, ASC, caspase-1, and NLRP3, forming a more complex PANoptosome to activate PANoptosis following ZIKV infection." (PMID 41263557, 2025). "Previous studies have shown that ZIKV infection activates the NLRP3 inflammasome, which leads to processing of pro-caspase-1 and secretion of IL-1β in infected monocytic cell lines, PBMC, or monocyte-derived macrophages." (PMID 35446851, 2022). "ZIKV infection activated NLRP3 inflammasome in HK-2 cells, which indicated by the increased expression level of NLRP3, ASC, cleaved-caspase-1, pro-IL-1β and mature IL-1β." (PMID 31474993, 2019). "Several genes involved in cell death (CASP1, TNFSF10, RIPK2, and BID) were also activated upon ZIKV infection." (PMID 30781519, 2019). "The body weights of infected mice were reduced during ZIKV infection, and such reductions were attenuated by Ac-YVAD-cmk, suggesting that Casp-1 or IL-1β is important for the infection of ZIKV." (PMID 29317641, 2018). "The survival rates of mice were reduced by ZIKV infection, and to our surprise, all infected mice survived in the presence of Ac-YVAD-cmk, further confirming that Casp-1 or IL-1β is important for the infection of ZIKV." (PMID 29317641, 2018). "In addition, GSDMD, a substrate of caspase-1, was cleaved to become cleaved GSDMD, an executor of pyroptosis, indicating that ZIKV infection activated inflammasomes, and induced pyrotosis, probably via a caspase-1-dependent canonical pathway." (PMID 35446851, 2022). "Consequently, we determined whether caspase-1 and GSDMD cleavage resulting from activation of the NLRP3 inflammasome were induced by ZIKV infection." (PMID 37191498, 2023).
ZIKV infection (continued). "Interestingly, ZIKV infection induces significant vascular permeability in the mime liver and kidney, and ZIKV-induced inflammatory responses are inhibited by Ac-YVAD-cmk, revealing that ZIKV induces inflammatory responses through Casp-1." (PMID 29317641, 2018).
fibrosis (10 papers, 2013 to 2025). the formation of excess fibrous connective tissue in an organ or tissue in a reparative or reactive process. "Whereas hyperoxia-placebo exposed rat pups had increased aortic fibrosis, as evidenced by Masson’s Trichrome staining of the aorta, treatment with caspase-1 inhibitor showed a trend to decrease fibrosis." (PMID 41231039, 2025). "Fibrosis in these disorders is mostly influenced by the interaction of the NF-κB/NLRP3/caspase-1/IL-1 axis and TGF-β signaling pathway." (PMID 37446339, 2023).
glioblastoma (10 papers, 2013 to 2025). The most malignant astrocytic tumor (WHO grade IV). "High levels of 4, 5-dimethoxycanthin-6-one can induce Caspase 1 expression, which eventually triggers the pyrogen death of glioblastoma cells." (PMID 35042538, 2022). "In addition, IP-Se-06 displayed significant inhibition of p38 MAPK and p-p38, leading to inhibition of inflammasome complex proteins (NLRP3 and caspase-1) in glioblastoma cells." (PMID 35360199, 2022). "In addition, the inhibition of MEK/ERK 1/2 signaling by IP-Se-06 resulted in antiproliferative activity, as well as in the inhibition of p38 mitogen-activated protein kinase, thereby leading to inhibition of inflammasome complex proteins, such as NLRP3 and caspase-1 in glioblastoma cells." (PMID 35360199, 2022). "targeted glioblastoma (GBM) using genetically modified Salmonella, whose lysis releases LPS that binds to TLR4 on host cells, activating the NLRP3-Caspase-1-GSDMD pathway and inducing pyroptosis." (PMID 39575419, 2024). "After the shKDELC2 transfection of the glioblastoma cells, there was a significant decrease in NLRP3, caspase-1, and IL-1β expression compared to the shLuc-transfected GBM8401 and U87 cells." (PMID 37107298, 2023). "We found that FK866 and CHS828, two distinct NAMPT inhibitors, increased the TMZ-induced apoptosis and necrosis, enhanced the TMZ-induced caspase-1, caspase-3, and caspase-9 activities, and augmented the TMZ-induced oxidative stress in glioblastoma cells." (PMID 28097126, 2016). "These correlations resulted in altered GBM (Glioblastoma Multiforme), in particular for CASP1." (PMID 25330190, 2014).